DYSF (dysferlin)
Diseases named in the same sentence as DYSF in open-access papers (continued):
Sharing a sentence is not in itself a finding about the gene and the disease.
muscular dystrophy (116 papers, 2007 to 2026). Muscular dystrophy (MD) refers to a group of more than 30 genetic diseases characterized by progressive weakness and degeneration of the skeletal muscles that control movement. "Remarkable is the fact that dysferlin has a different expression pattern from other muscle proteins associated with muscular dystrophy." (PMID 39747848, 2025). "Histologically, dysferlin-deficient muscles resemble those of other muscular dystrophies, characterized by fiber atrophy, centralized nuclei, immune cell infiltration, and replacement of muscle by fat and fibrotic tissue." (PMID 40021220, 2025). "Dysregulated Ca handling linked to RyR dysfunction is reported in several muscular dystrophies, including Duchennes, dysferlin-related LGMD R2, β-sarcoglycan-related LGMD R4, and calpain 3-related LGMD R1." (PMID 41357548, 2025). "Mutations in the dysferlin gene (DYSF) can result in rare forms of muscular dystrophy; Miyoshi myopathy; limb girdle muscular dystrophy type 2B (LGMD2B); and distal myopathy." (PMID 38891760, 2024). "Dysferlin is one of the most important proteins in the sarcolemmal repair process, although deficiencies of any protein in this repair complex would lead to muscular dystrophy, a heterogeneous group of muscle-wasting diseases." (PMID 38891760, 2024). "The DYSF gene encodes the protein Dysferlin, mainly associated with muscular dystrophy following an AR pattern of inheritance." (PMID 37035729, 2023). "These membrane repair proteins have been shown to contribute to human disease; disruption of the TRIM72/MG53, caveolin-3, and dysferlin complex, as well as mutations in the dysferlin and caveolin-3 genes, can result in muscular dystrophies." (PMID 35563723, 2022). "Mutations in DYSF cause Dysferlinopathies, a group of muscular dystrophies composed of LGMDR2 (formerly LGMD2B; OMIM: 253601), Miyoshi Muscular Dystrophy 1 (MMD1; OMIM: 254130) and Myopathy, Distal, With Anterior Tibial Onset (DMAT; OMIM: 606768)." (PMID 34740639, 2022). "DYSF has been one of the first identified key membrane-repair proteins, whose deficiency leads to a membrane repair defect and the development of muscular dystrophy." (PMID 34067866, 2021). "In 2003, Bansal and collaborators revealed for the first time a direct link between a failure in membrane repair, caused by mutations in DYSF gene, and the development of a muscular dystrophy, e.g., LGMDR2 (2B)." (PMID 34067866, 2021). "The patient with CAPN1 and DYSF pathogenic variants did indeed have a severe muscle weakness attributed to the muscular dystrophy." (PMID 33486633, 2021). "Mutations in dysferlin and otoferlin genes cause heredity diseases: muscular dystrophy and deafness in humans, respectively." (PMID 33182221, 2020). "The QTL on BTA5 which contained the AMDHD1 gene, was located close to a QTL previously associated with carcass composition, whereas the QTL on BTA11 contains DYSF, a gene known to be linked with muscular dystrophy in humans." (PMID 32000665, 2020). "The best established link between repair deficiency and disease phenotype is observed in muscular dystrophies, such as dysferlin-deficient muscular dystrophy, where a failure to repair repeated membrane lesions leads to progressive muscle wasting." (PMID 32326222, 2020). "Among six ferlins, dysferlin and otoferlin mutations cause genetic diseases in humans: muscular dystrophy and deafness, respectively." (PMID 33182221, 2020). "Two missense variants in DYSF were found (c.779C>G and c.2997G>T), and based on this, the patient was diagnosed with muscular dystrophy, limb‐girdle type 2B." (PMID 31475473, 2019). "Muscular-dystrophy patients carrying the V705M dysferlin variant have been diagnosed with Miyoshi Myopathy40, and present with weakness in the distal skeletal muscles." (PMID 30026467, 2018). "This study describes the emergence of a progressive hip region muscular dystrophy in Bla/J dysferlin‐deficient mice and relates muscle atrophy to decreased physical abilites." (PMID 28320887, 2017).
muscular dystrophy (continued). "The class of muscular dystrophies linked to the genetic ablation or mutation of dysferlin, including Limb Girdle Muscular Dystrophy 2B (LGMD2B) and Miyoshi Myopathy (MM), are late-onset degenerative diseases." (PMID 24639655, 2014). "Immunohistochemical analysis of sarcolemmal proteins in muscle biopsies like dystrophin, SGCs, merosin, and dysferlin is an important part of the diagnostic evaluation of patients with muscular dystrophy." (PMID 25050186, 2014). "The roles of dysferlin and myoferlin in membrane fusion events have primarily focused on skeletal muscles, as mutations particularly in the dysferlin gene are associated with the development of muscular dystrophy, a muscle wasting disease." (PMID 22808170, 2012). "Two strains, A/J and SJL/J, are known to develop muscular dystrophy with age due to null mutations in the dysferlin gene (Dysf)." (PMID 21853140, 2011). "Defective membrane repair in dysferlin-deficient muscle leads to the development of muscular dystrophy associated with remarkable muscle inflammation." (PMID 21798087, 2011). "These innate pathways contribute significantly to the development of inflammatory disorders, kidney disease, and metabolic diseases, and inflammasome components are upregulated in dysferlin-deficient muscular dystrophy." (PMID 21850221, 2011). "Accumulating evidence indicates that ‘presymptomatic’ activation of inflammatory pathways is a common feature of other, later-onset forms of muscular dystrophy as well, including those caused by deficiencies in dysferlin or dystrophin." (PMID 21850221, 2011). "In the present work using mouse models, we have further demonstrated that a double-deficiency in both dystrophin and dysferlin results in more severe muscular dystrophy." (PMID 22132688, 2011). "Mutations in the genes coding for either dystrophin or dysferlin cause distinct forms of muscular dystrophy." (PMID 22132688, 2011). "A defect in either mechanism is detrimental to the muscle, as manifested by the fact that genetic mutations in either the DGC components or dysferlin cause various muscular dystrophies." (PMID 22132688, 2011). "Dysferlin was previously identified as a key player in muscle membrane repair and its deficiency leads to the development of muscular dystrophy and cardiomyopathy." (PMID 22110769, 2011). "Mutations in dysferlin underlie an autosomal recessive form of muscular dystrophy (limb girdle muscular dystrophy type 2B, LGMD2B and the allelic disorder Miyoshi myopathy)." (PMID 20667140, 2010). "Miyoshi Myopathy (MM) is a distinct form of muscular dystrophy caused by mutations within the dysferlin (DYSF) gene resulting in severe to complete deficiency of dysferlin expression." (PMID 20497525, 2010). "Dysferlinopathies are recessive inherited muscular dystrophies caused by mutation of the dysferlin gene (DYSF) mapped to human chromosome 2p13." (PMID 20618995, 2010). "Mutations in dysferlin result in progressive muscular dystrophies and dysferlin appears to be required for Ca2+-dependent sarcolemma resealing during membrane repair in skeletal muscle fibres." (PMID 19180193, 2009). "In sum, we developed a toolbox across cell-types and species to translate repair of an important DYSF founder mutation into clinical application and demonstrate the first in vivo rescue of a muscular dystrophy by autologous transplantation of gene-edited primary MuSC." (PMID 39747848, 2025). "DYSF is well known for its expression in muscle cells, where a deficiency may cause muscular dystrophy." (PMID 40352730, 2025). "Dysferlin-deficient muscular dystrophy is a devastating and untreatable disease." (PMID 39747848, 2025). "Several studies have also investigated DYSF variants and their association with muscular dystrophy." (PMID 38539162, 2024). "There was no striking glycogen staining in these mdx muscles, emphasising that high glycogen in dysferlin-deficient muscles (with marked histopathology) may be specific for this muscular dystrophy." (PMID 39123261, 2024).
muscular dystrophy (continued). "Limb-girdle muscular dystrophy R2 (LGMDR2) (previously called LGMD2B) is genetically determined muscular dystrophy with autosomal recessive transmission due to mutations in the DYSF gene leading to sarcolemma repair abnormalities and secondary inflammatory activation." (PMID 37936913, 2023). "Indeed, dysferlin deficient mice have defective calcium-dependent sarcolemmal repair and display a progressive muscular dystrophy that mirrors the pathology seen in biopsies from affected individuals." (PMID 36653852, 2023). "Co-immunoprecipitation has revealed that annexin-A1 associates with dysferlin in a calcium- and membrane-injury-dependent manner, a behavior consistent with reported involvement of multiple annexins in muscle repair and muscular dystrophy (e.g., annexin A11)." (PMID 36902136, 2023). "However, during muscular dystrophy (linked to mutations in the caveolin gene), CG endocytosis promotes dysferlin surface retention by increasing its exit from the Golgi complex, which signifies its pathological role." (PMID 36010634, 2022). "Notably, DYSF is responsible for muscle membrane repair machinery during muscle degeneration, and its function loss is associated with adipogenic loss in muscular dystrophy." (PMID 35681201, 2022). "Thus, while both dystrophin and dysferlin are expressed in the endothelium and are associated with the development of muscular dystrophies, they play vastly different roles in vascular homeostasis and indeed the progression of vascular disease." (PMID 34366880, 2021). "The cell’s reliance on the PMR process is even greater in mechanically active tissues such as skeletal muscle, where PM injury is frequent and failure to repair leads to degenerative diseases such as muscular dystrophies, including limb girdle muscular dystrophy 2B caused by mutations in dysferlin." (PMID 32824910, 2020). "DYSF mutations are associated with muscular dystrophy in humans and mice." (PMID 32973871, 2020). "Like dysferlin, many mutations of Cav3 have been linked to muscular dystrophy." (PMID 33240103, 2020). "The importance of ANXA6 in muscle cell plasma membrane repair was recognized when mutations of the ANXA6 gene were found to negatively impact the phenotype of dysferlinopathy (a group of rare muscular dystrophies with recessive mutations in the dysferlin gene)." (PMID 32326222, 2020). "This work might contribute to a better understanding of the mechanisms involved in the pathogenesis of muscular dystrophies caused by mutations in dysferlin." (PMID 31861684, 2019). "The class of muscular dystrophies linked to the genetic ablation or mutation of dysferlin, including Limb Girdle Muscular Dystrophy 2B (LGMD2B) and Miyoshi Myopathy (MM), are degenerative diseases of skeletal muscle that typically appear in the teen years and ultimately lead to loss of mobility." (PMID 24639655, 2014). "Dysferlin-deficient mice show defective membrane repair and also develop muscular dystrophy." (PMID 25198651, 2014). "However, loss of dysferlin staining is well recognised secondary phenomena in other limb girdle muscular dystrophies, most well characterised in mutations in caveolin-3 (LGMD 1C)." (PMID 23641709, 2013). "Mutations in dysferlin cause muscular dystrophy, but development of dilated cardiomyopathy is rare." (PMID 22427904, 2012). "A genetic approach using complement-deficient mice with the disrupted expression of C3, a central component of the complement system, further confirmed the active role of complement activation in the progression of muscular dystrophy in dysferlin-deficient mice." (PMID 21798087, 2011). "Indeed, the discovery of DYSF variants and the resulting capacity to offer genetic diagnosis remains the essential first step in enabling all future clinical advancements for this form of muscular dystrophy." (PMID 38539162, 2024).
muscular dystrophy (continued). "Notably, aggregation and reduced PM association of dysferlin are observed in several muscular dystrophies including caveolinopathies and sarcoglycanopathies suggesting that dysferlin mis-targeting could also play a role in the pathogenesis of these diseases." (PMID 26301073, 2015). "In addition, it has been reported that dysferlin deficiency leads to increased expression of complement factors and that complement-mediated muscle injury is associated with the pathogenesis of dysferlin-deficient muscular dystrophy." (PMID 25198651, 2014). "Moreover, a down-regulation of the complement inhibitory factor, CD55 in the skeletal muscle of mice and patients with DYSF-deficient muscular dystrophy was recently demonstrated, resulting in an increased susceptibility of DYSF-deficient human myotubes to complement attack in vitro." (PMID 20618995, 2010). "Limb–girdle muscular dystrophy type R2 (LGMDR2, formerly called LGMD2B) is an autosomal recessive form of muscular dystrophy (MD) caused by pathogenic variants in the DYSF gene, which leads to dysferlin deficiency." (PMID 40814795, 2025). "Defects in DYSF can manifest as different types of muscular dystrophy based on clinical presentation." (PMID 38891760, 2024). "Variants in the dysferlin gene (DYSF), which encode DYSF (MIM*603,009), are associated with an autosomal recessive disorder characterized by various clinically distinct muscular dystrophies, including LGMD." (PMID 38539162, 2024). "In PID_5, a novel heterozygous frameshift insertion in DYSF was identified, which accounts for muscular dystrophy." (PMID 38057384, 2023). "Dysregulations in annexin-family proteins, calpains, MG53, and dysferlin are involved in the development of muscular dystrophies." (PMID 37008019, 2023). "Under physiological conditions, caveolin-1 or -3 increases the surface retention of dysferlin, whereas during muscular dystrophy, CG endocytosis promotes its surface retention by increasing its exit from the Golgi complex." (PMID 36010634, 2022). "Of note, the proteins encoded by genes linked to other muscular dystrophies such as COL6A1, CAV3, DYSF, DMD, TTN, and VCP and the strongest family sequencing candidates INTS1 and ANK2 were all found in nuclear envelope proteomics datasets." (PMID 31862442, 2020). "In contrast, dysferlin-deficient mice grow normally up to a certain age and later develop muscular dystrophy, emphasizing functional differences between myo- and dysferlin in mice." (PMID 32106631, 2020). "Corroborating our data here, another report observes elevated miR-142-3p levels in the gastrocnemius of three distinct muscular dystrophy model mice: Dysferlin-null, α−sarcoglycan (Sgca)-null, and mdx." (PMID 29883261, 2018). "Disruption of membrane stability due to the loss of dystrophin-glycoprotein complex (DGC) or membrane repair capacity due to the defect in dysferlin has been widely reported to be responsible for various types of muscular dystrophies." (PMID 26693275, 2015). "Other milder forms of muscular dystrophy are caused by mutations in genes coding the enzyme calpain 3 (LGMD2A), the sarcolemmal protein dysferlin (LGMD2B), and the sarcomeric protein telethonin (LGMD2G)." (PMID 25221510, 2014). "For example, genetic defects in the DYSF gene lead to the development of multiple muscular dystrophies." (PMID 22110769, 2011). "Secondary sarcolemmal reduction of dysferlin is often seen in muscle biopsies of patients with many other forms of muscular dystrophy but in all these cases the band for dysferlin is normally detected on immunoblot." (PMID 21798100, 2011). "In the animal model of DYSF deficiency, i.e. the mutant SJL mouse strain, the disease process was initially considered an 'inflammatory' form of muscular dystrophy." (PMID 20618995, 2010). "Mammals have several ferlin genes and mutations in the human dysferlin (DYSF) and otoferlin (OTOF) genes result in muscular dystrophy and hearing loss, respectively." (PMID 17386097, 2007).
muscular dystrophy (continued). "Previous work has highlighted similar compensatory mechanisms in dysferlin-deficient muscular dystrophy, a muscular disorder without myocardial involvement." (PMID 39625536, 2024). "Variation in dysferlin localization is a common characteristic of muscular dystrophies." (PMID 37686363, 2023). "Notably, the CG pathway determines the subcellular localization of dysferlin (a skeletal muscle repair protein) in muscular dystrophy." (PMID 36010634, 2022). "Remarkably, to date, no report has been published with mutations in dysferlin exon 40a associated with a muscular dystrophy presentation." (PMID 34888307, 2021). "Loss-of-function mutations in dysferlin results in human muscular dystrophy, and mice lacking dysferlin (Dysf) display similar pathological features to the human disorder." (PMID 34354129, 2021). "This was suggestive of classical autosomal recessive Miyoshi myopathy caused by compound heterozygous or homozygous dysferlin gene mutation(s), since neither of their parents had been diagnosed with muscular dystrophy." (PMID 29879922, 2018). "The majority of studies on dysferlin function have been in the context of muscular dystrophy." (PMID 24454878, 2014). "We conclude that dysferlin has the potential to protect muscular dystrophy progression; however, its effect may depend on disease severity and the amount/activity of dysferlin proteins." (PMID 25198651, 2014). "As with other forms of muscular dystrophy, adeno-associated virus (AAV) gene transfer is a particularly auspicious treatment strategy, however the size of the DYSF cDNA (6.5 kb) negates packaging into traditional AAV serotypes known to express well in muscle (i.e. rAAV1, 2, 6, 8, 9)." (PMID 22720081, 2012). "Given that autophagic deficits are complicators of tissue recovery in various neuromuscular disorders, including also muscular dystrophies due to COL6 and DYSF deficiencies, the expansion of the compound’s potential applicability could also reach beyond DMD treatment." (PMID 39859157, 2025). "However, unlike dysferlin, no clinical forms of muscular dystrophy due to mutations in myoferlin have been reported." (PMID 34354129, 2021). "A novel nonsense C > G mutation located at position 4299 in exon 39 (NCBI RefSeq: NM_003494) of the dysferlin gene (DYSF) was identified as responsible for the family’s muscular dystrophy after filtering out common variants and those not predicted to impact protein function." (PMID 29879922, 2018). "In conclusion, our data demonstrate that myoferlin and a minidysferlin can compensate for dysferlin-deficiency in an in vitro assay of sarcolemmal repair but not for the defects in muscle in vivo that lead to muscular dystrophy associated with the absence of dysferlin." (PMID 22666441, 2012). "Immunohistochemical staining of dysferlin, ORO, and PAS in patients with suspected muscular dystrophy and metabolic myopathy are helpful for clinicians to exclude IMNM from muscular dystrophy and metabolic myopathy." (PMID 35524238, 2022). "MG53 has been shown to interact with dysferlin and participate in membrane repair, and genetic disruption of MG53 in mice results in muscular dystrophy." (PMID 25198651, 2014). "The dataset includes 13 muscular dystrophy related phenotypes, i.e. ALS, AQM, BMD, Calpain3, DMD, Dysferlin, Lamin A/C, Emerin, FKRP, FSHD, HSP, JDM, and NHM." (PMID 18801195, 2008). "Mouse models lacking dysferlin develop muscular dystrophy, however, with an apparently less severe phenotype than humans and do not lose ambulation with age." (PMID 32106631, 2020). "Dysferlin has been well studied because of its involvement in forms of muscular dystrophy but it has never been reported to be present in the RBC membrane in previous proteome analyses." (PMID 24454878, 2014).